CHP2 (calcineurin like EF-hand protein 2)
Description:
Functions as an integral cofactor in cell pH regulation by controlling plasma membrane-type Na(+)/H(+) exchange activity. Binds to and activates SLC9A1/NHE1 in a serum-independent manner, thus increasing pH and protecting cells from serum deprivation-induced death. Also plays a role in the regulation of cell proliferation and tumor growth by increasing the phosphatase activity of PPP3CA in a calcium-dependent manner. Activator of the calcineurin/NFAT signaling pathway. Involved in the cytoplasmic translocation of the transcription factor NFATC3 to the nucleus.
Tractability: Small molecule: it has a binding pocket of medium quality. Antibody: UniProt places it where antibodies can reach, with high confidence; its Gene Ontology location is reachable by antibodies, with high confidence.
Gene: Protein-coding gene on chromosome 16 (23,754,618 to 23,758,951, forward strand). Ensembl gene ENSG00000166869.
Subcellular location: Nucleus; Cytoplasm; Cell membrane
Subcellular location (Human Protein Atlas): Nucleoplasm; Cytosol; Nucleoli
Gene Ontology:
Molecular function: calcium ion binding; protein binding
Biological process: cellular response to calcium ion; positive regulation of calcineurin-NFAT signaling cascade; positive regulation of cell population proliferation; positive regulation of phosphatase activity; positive regulation of protein import into nucleus; positive regulation of transcription by RNA polymerase II; intracellular sodium ion homeostasis; regulation of intracellular pH; regulation of calcineurin-NFAT signaling cascade; regulation of protein import into nucleus
Cellular component: cation-transporting ATPase complex; cytoplasm; cytosol; nucleolus; nucleoplasm; nucleus; plasma membrane; basolateral plasma membrane
Genetic constraint (gnomAD): Loss-of-function variants: 31 observed, 25.24 expected, observed/expected ratio (o/e) 1.23, 90% interval 0.92 to 1.65. The upper end of that interval is the gene's LOEUF score, 1.65, which puts it in group 6 of 6, group 1 being the genes least tolerant of losing a copy. Missense variants: 319 observed, 269.69 expected, observed/expected ratio (o/e) 1.18, 90% interval 1.08 to 1.3. Synonymous variants: 97 observed, 100.16 expected, observed/expected ratio (o/e) 0.97, 90% interval 0.82 to 1.15.
Homologues: Orthologues: chimpanzee CHP2 (100% identical), macaque CHP2 (99% identical), dog CHP2 (88% identical), pig CHP2 (88% identical), guinea pig CHP2 (85% identical), rabbit CHP2 (83% identical), mouse Chp2 (81% identical), rat Chp2 (81% identical), Drosophila melanogaster elm (47% identical), Caenorhabditis elegans chpf-2 (46% identical), Caenorhabditis elegans chpf-1 (45% identical), Drosophila melanogaster CG32812 (31% identical), and 3 more. Paralogues in human: CHP1 (61% identical), PPP3R1 (32% identical), PPP3R2 (32% identical), TESC (28% identical), CIB2 (24% identical), CIB4 (22% identical), CIB1 (21% identical), CIB3 (20% identical).
Diseases named in the same sentence as CHP2 in open-access papers:
CHP2 is named in the same sentence as 18 diseases in open-access papers, as found by Europe PMC text mining. Sharing a sentence is not in itself a finding about the gene and the disease. The quoted sentences say what the papers report.
breast carcinoma (4 papers, 2020 to 2025). "The expression of CHP2 has been reported to be significantly increased in human ovarian carcinoma cells and leukemia primary cells and breast cancer cells." (PMID 32256214, 2020). "CHP1 is expressed ubiquitously in all tissues, whereas CHP2 is expressed in the small intestine and several cancers, including hepatic carcinoma, leukemia, breast cancer, and ovarian cancer." (PMID 32365487, 2020). "Inhibition of chp2 in breast cancer cells can delay the G1-S cell cycle transition." (PMID 37162816, 2022). "Mechanistically, overexpression of CHP2 activated AKT signaling and suppressed the transactivation of the forkhead box O3 (FOXO3/FOXO3a) transcription factor in breast cancer." (PMID 32256214, 2020).
colorectal cancer (2 papers, 2022 to 2026). A primary or metastatic malignant neoplasm that affects the colon or rectum. "Taking the AUC and P.values into account, the ROC curves showed that CHP2 and MSLN genes can play role as high-quality markers in colorectal cancer." (PMID 35333898, 2022).
hepatic carcinoma (2 papers, 2020 to 2025). "CHP2 functions as a tumor-associated antigen in several cancers and was initially identified in hepatocellular carcinoma as HCA520." (PMID 40723891, 2025).
bone sarcoma (1 paper, 2026). A sarcoma that arises from the bone. "Under stress conditions, CHP2 action is associated with NHE1 activity, supporting CHP2 as a conditional modulator of malignant behavior in human bone sarcoma cells." (PMID 41749826, 2026). "Calcineurin Homologous Protein 2 (CHP2) is a binding partner and functional regulator of NHE1 that is preferentially expressed in cancer cells; however, its role in bone sarcoma biology remains undefined." (PMID 41749826, 2026).
cholangiocarcinoma (1 paper, 2020). A carcinoma that arises from the intrahepatic biliary tree (intrahepatic cholangiocarcinoma) or from the junction, or adjacent to the junction, of the right and left hepatic ducts (hilar cholangiocarcinoma). "However, unlike the expression of TESC, we found that CHP1 is dominantly expressed in normal tissues and that the expression of CHP2 does not differ significantly between cholangiocarcinoma and adjacent non-tumor tissues." (PMID 32365487, 2020).
co-infection (1 paper, 2025). "Interestingly, the results showed that each H. pylori strain (CHP1, CHP2, CHP3, and CHP4) infection alone or co-infection with EBV led to reduced growth of NGOs, when compared to the mock group." (PMID 40833108, 2025). "Four strains (CHP1, CHP2, CHP3, and CHP4) of H. pylori from gastric tissues of patients, who exhibited disparate clinical symptoms and tumor types, were isolated and tested for co-infection." (PMID 40833108, 2025).
cystic fibrosis (1 paper, 2025). Autosomal recessive disorder caused by pathogenic variants in the CFTR gene (cystic fibrosis transmembrane conductance regulator), which encodes a chloride and bicarbonate channel expressed in epithelial cells, and follow the diagnosis criteria. "Additionally, a genome-wide association study (GWAS) using whole genome data from cystic fibrosis patients discovered that the CHP2 region on chromosome 16, which is related to MAC infection, is associated with severe cystic fibrosis." (PMID 40176807, 2025).
lung disease (1 paper, 2020). "However, only CHP2 and PRKCB in the chr16 region are consistently associated with CF lung disease by expression imputation." (PMID 33253230, 2020).
melanoma (1 paper, 2013). A malignant, usually aggressive tumor composed of atypical, neoplastic melanocytes. "This leaves WNT4, CHP2, PPP2R2C and COL11A1 which have not been previously reported to be associated with melanoma." (PMID 23638386, 2013). "However, six signature genes (i.e., IL8, SHC4, COL11A1, CHP2, PPP2R2C and WNT4) were not reported previously by microarray-based melanoma studies, although two (i.e. IL8 and SHC4) have been identified in independent wet-lab studies." (PMID 23638386, 2013).
reactive arthritis (1 paper, 2024). Reactive arthritis (ReA) is an autoimmune disorder belonging to the group of seronegative spondyloarthropathies and is characterized by the classic triad of arthritis, urethritis and conjunctivitis. "Notably, a Microviridae member v0185 carried a gene encoding the Chlamydia phage Chp2 scaffold protein, suggesting its possibility of infecting Chlamydia species that were commonly related to reactive arthritis." (PMID 38872164, 2024).
sarcoma (1 paper, 2026). A usually aggressive malignant neoplasm of the soft tissue or bone. "Serum deprivation did not significantly alter CHP1 or CHP2 protein expression; however, silencing of CHP2 reduced NHE1 activity under serum-deprived conditions and significantly decreased migration and proliferation in both sarcoma cell lines." (PMID 41749826, 2026).
cancer (8 papers, 2014 to 2026). A tumor composed of atypical neoplastic, often pleomorphic cells that invade other tissues. "While the expressional alteration of CHP2 gene has been validated by the validation dataset its methylation status was confirmed only in COAD cancer type by the MEXPRESS." (PMID 35333898, 2022). "We showed that the genes encoding ANPEP, PROK2, CHP2, PTPRM, AREG, and COL7A1 were differentially expressed between SRC and PC carcinomas." (PMID 35626106, 2022). "Genes encoding ANPEP, PROK2, CHP2, PTPRM, AREG, and COL7A1 showed significant differential expression in SRC and PC carcinomas." (PMID 35626106, 2022). "In these six cancer-related pathways, four genes (IL8, PRLR, EFNA1, and CHP2) were uniquely regulated by one specific miRNA each (hsa-miR-338-5p_IL8, hsa-miR-338-5p_PRLR, hsa-miR-760_EFNA1, hsa-miR-450b-5p_CHP2)." (PMID 26259570, 2015).
neurodegenerative disease (1 paper, 2017). A disorder of the central nervous system characterized by gradual and progressive loss of neural tissue and neurologic function. "Chp1 was required for axon degeneration in many neurodegenerative diseases, and Chp2, the homologous gene of Chp1, could enhance the oncogenic potential of HEK293 cells through activating the calcineurin/nuclear factor signaling pathway in activated T cells." (PMID 29383134, 2017).
CHP2 also shares sentences with these, for which no sentence is quoted: ovarian carcinoma (3 papers); tumor (3); leukemia (2); infection (1); lung carcinoma (1).